RUNX2 (RUNX family transcription factor 2)
Diseases named in the same sentence as RUNX2 in open-access papers (continued):
Sharing a sentence is not in itself a finding about the gene and the disease.
tumor (continued). "To date, a large body of evidence suggests that Runx2 is closely associated with tumor metastasis." (PMID 35342401, 2022). "Moreover, in the tumor cells, RUNX2 is known to be associated with increased cell migration and proliferation, but not with osteogenic differentiation." (PMID 34829835, 2021). "In conclusion, these findings support the idea that the Runt domain of Runx2 is involved in increasing the risk of tumour proliferation/migration and angiogenesis, and may be an ideal oncotarget in melanoma cancer cells." (PMID 31142788, 2019). "Recent studies have shown that Runx2 was associated with tumor cell invasion and metastasis." (PMID 28264434, 2017). "The in vitro data showed that Runx2 might play an important role in tumor cell invasion and migration and be closely associated with VE-cadherin expression and tumor cell plasticity to VM pattern." (PMID 28264434, 2017). "Since RUNX2 is a transcription factor, we used bioinformatics analysis to identify genes potentially targeted by RUNX2 W. Among genes linked to tumor cell invasion and metastasis, six candidates were identified with the highest score for the gene encoding a chemokine receptor CXCR4." (PMID 27007162, 2016). "In addition, RUNX2 regulates the expression of genes closely associated with tumor progression, invasion and metastasis and has pro-angiogenic effects." (PMID 27102439, 2016). "RUNX2 regulates the expression of genes intimately associated with tumor progression, invasion and metastasis and its role in migration and invasion has been documented in different tumor cell types." (PMID 26204939, 2015). "Our data suggest that RUNX2 is possibly implicated in EOC tumor and cancer cell growth and invasion and could represent a potential EOC therapeutic target." (PMID 24124450, 2013). "In most of these studies, RUNX2 was functionally associated with tumor invasion and metastasis." (PMID 24124450, 2013). "Lately, RUNX2 expression was also associated with EOC tumor progression and poor prognosis." (PMID 24124450, 2013). "RUNX2 encodes a transcription factor important in osteogenesis and has been expressed in up to 87% of tumour specimens, including biopsy samples, implying that alteration of 6p12-p21 may be an early event in the disease." (PMID 22685381, 2012). "Given that FASN and RUNX2 are also associated with immune-related pathways, including cytokine signaling and immune cell infiltration, their lactate-regulatory roles may exert multifaceted effects that go beyond intrinsic tumor growth." (PMID 40703521, 2025). "In addition to its role in tumor biology, RUNX2 is implicated in the vasculature." (PMID 41511334, 2025). "Thus, RUNX2 expression in the GC we found in the blood of MDS patients could be linked to the tumor characteristics of the GC, increasing the probability for the GC to be, in fact, PGCC." (PMID 37316755, 2023). "Therefore, RUNX2 could become an essential biomarker for developing diagnostic tools and specific treatments against tumoral diseases in the lung after the experimental validation of its regulatory function." (PMID 36551878, 2022). "Studies have shown that RUNX2 is involved in tumor cell migration and invasion 23 and that RUNX2 directly targets the MMP1 promoter in TNBC cells." (PMID 40386045, 2025). "In simpler terms, RUNX2 can be thought of as a “switch” that promotes bone-like, invasive behavior in tumor cells." (PMID 41141138, 2025). "Targeting the RUNX2–HIF-1α interaction or its downstream angiogenic mediators holds promise for curbing tumour-induced neovascularization and impeding metastatic progression within bone tissue." (PMID 40806771, 2025). "We also found that RUNX2 expression levels correlated with tumor stage (P = 0.000123), tumor grade (P = 9.41e-07), and overall survival (P = 1.98e-06)." (PMID 40386045, 2025).
tumor (continued). "On the other side, mononuclear cells were mostly positive for osteoblast markers such as RUNX2, SATB2, and KPNA-2, whereas tumor-associated macrophages showed positivity for Iba1." (PMID 40075982, 2025). "Our study found that its expression is significantly correlated with cytokine-cytokine receptor interactions and cancer-related pathways, suggesting the potential value of Runx2 in tumor progression and immune regulation." (PMID 40703521, 2025). "This rationale can be tested using 3D tumor spheroids or organoids with tunable stiffness, coupled with RUNX2–SREBP1 inhibition and metabolic assays." (PMID 41511334, 2025). "Given its central involvement in tumor progression, RUNX2 is emerging as a promising therapeutic target, with ongoing research focused on elucidating its regulatory networks and developing RUNX-targeted treatment strategies in bone malignancies." (PMID 40507962, 2025). "Our data suggest that RUNX2 not only regulates fibrotic genes but also serves an important mediator linking immune responses and tumor progression." (PMID 40826474, 2025). "Beyond its physiological role, increasing evidence implicates RUNX2 in cancer biology by regulating tumor-related signaling pathways and downstream effectors." (PMID 40507962, 2025). "Among all the osteoblast-derived molecules released by tumor cells, Runx2 has been suggested as a regulator of OPN expression, however the microenvironmental factors driving this mechanism are poorly described." (PMID 40753365, 2025). "The box plot illustrated a clear distinction between the groups, and IHC staining revealed pronounced nuclear RUNX2 positivity in tumor cells." (PMID 41141138, 2025). "SREBP1 activation has been reported in stiff tumor environments suggesting that biomechanical forces can trigger the RUNX2–SREBP1 relationship." (PMID 41511334, 2025). "Our data suggest that through its transcriptional activity -both as activator and repressor of gene expression- RUNX2 can synchronize these functions to ensure the most advantageous metabolic asset for tumor cells." (PMID 41174748, 2025). "Although these findings provide strong mechanistic insights into the tumor-suppressive role of WWOX through modulation of RUNX2, direct investigations of this molecular pathway in ES have not been published." (PMID 41141138, 2025). "When these modified cells were transplanted into immunodeficient mice, RUNX2 suppression significantly slowed down primary tumor growth, demonstrating its therapeutic potential." (PMID 40781158, 2025). "Conversely, RUNX2 overexpression appears to be a defining characteristic, potentially influencing tumor proliferation, osteogenic signaling, and metastatic potential." (PMID 41141138, 2025). "Taken together, our findings propose a novel mechanistic axis—centered on FASN and RUNX2—linking metabolic enzymes to protein lactylation and downstream tumor-promoting processes." (PMID 40703521, 2025). "HIF-1α alters the tumour microenvironment and promotes angiogenesis and glycolysis, whereas RUNX2 is an important bone transcription factor." (PMID 40806771, 2025). "These macrophages physically intermingle with RUNX2 high/PD-L1 high osteoblastic tumour cells and with SPP1+ osteoclast progenitors, forming an immunosuppressive triad that is virtually devoid of granzyme-B+ cytotoxic lymphocytes." (PMID 40740859, 2025). "In CRC, CBX4 acts as a tumor suppressor by interacting with histone deacetylase 3 (HDAC3) to repress the expression of the (runt-related transcription factor 2) RUNX2 gene, which activity promotes metastasis in CRC cell lines and mice model." (PMID 40175347, 2025). "Such as miR-150, enhanced anti-tumour properties and increases the sensitivity to chemotherapy by suppressing RUNX2 expression." (PMID 40806771, 2025). "LEF1 and RUNX2 were identified as highly active transcription factors in the calcification subtype of tumor cells." (PMID 39483146, 2024).
tumor (continued). "Evidently, RUNX2 generally acts as a tumor facilitator, often collaborating with other signaling pathways to exacerbate cancer progression." (PMID 38430423, 2024). "In LUAD, RUNX2 functions as a critical transcription factor that augments tumor cell EMT, migration, and invasion through the upregulation of the galectin-3 pathway and ROS activation." (PMID 38430423, 2024). "Essential for bone formation, RUNX2 aberrantly overexpresses in specific tumor cells of breast and prostate origin, which eventually manifest invasive bone metastases." (PMID 38430423, 2024). "In BLCA, aberrantly overexpressed RUNX2 contributes to tumor metastasis by inducing an EMT phenotype." (PMID 38430423, 2024). "RUNX2 exerts a pivotal influence on the regulation of tumor stemness across a diverse array of cancer subtypes." (PMID 38430423, 2024). "Runx2 is a potential therapeutic target for bone metastasis due to its role in regulating the behavior of tumor cells and stroma in humans." (PMID 39595568, 2024). "In various tumours, RUNX2 expression is deregulated by different miRNAs, circRNAs, and regulatory proteins." (PMID 37759525, 2023). "Circ_001722 is a novel tumor promotor in OS, and promotes the progression of OS via miR-204-5p/RUNX2 axis." (PMID 37453970, 2023). "For example, the lncRNA called HAND2-AS plays a tumour-suppressive role in liver cancer and prohibits hepatoma cancer cell proliferation by decreasing the expression level of RUNX2." (PMID 37759525, 2023). "In another study of ccRCC, the biological function of RUNX2 was to increase focus formation, Ki67-positive staining, and tumor volume in a xenograft model." (PMID 37108164, 2023). "Subsequent transcriptomic and epigenomic data integration has allowed us to reveal subtype‐specific molecular pathways governed by AP‐1, SMAD3 and RUNX1/RUNX2 transcription factors (TF) in both pd‐GBSCs and bulk tumours." (PMID 37357610, 2023). "In human non-small cell lung cancer (NSCLC), increased expression of RUNX2 is significantly correlated with tumor size, tumor stage, and lymph node metastasis." (PMID 36897488, 2023). "Elevated RUNX2 levels can transcriptionally activate genes that mediate tumor progression and metastasis, including the RUNX2 target gene osteopontin (OPN/SPP1) in OS." (PMID 37240338, 2023). "In the tumor context, it has been shown that RUNX2 plays a crucial role in the invasion and metastasis of cancers." (PMID 37754231, 2023). "Among them, RUNX1 was relatively more highly expressed than the other two RUNX genes, and the significant difference in RUNX1 expression between tumor and para-tumor tissues excluded the role of RUNX2 and RUNX3, suggesting the importance of abundant RUNX1." (PMID 37697370, 2023). "Correlated modulation of gene expression between panobinostat treatment and silencing of HEY1-NCOA2 or Runx2 indicated that downregulation of target genes by HEY1-NCOA2 and Runx2 cooperation, at least in part, is important for tumor cell maintenance." (PMID 37212282, 2023). "As revealed by the western blot, RUNX2 and β‐catenin protein expression were higher in tumor tissues than that in the adjacent normal tissues." (PMID 36200301, 2023). "We detected recurrent activation of miR-140 leading to upregulated RUNX2 expression in high-grade patient tumours." (PMID 36936386, 2023). "As a regulatory molecule, RUNX2 has been a part of molecular networks that promote the invasive behaviour of tumours." (PMID 37759525, 2023). "miR-320b acts as a tumor suppressor during OS invasion and migration by directly suppressing RUNX2 expression." (PMID 37240338, 2023). "Studies on RUNX2-related regulatory mechanisms hint at its pro-invasive functions in HCC by reshaping the tumour microenvironment, making RUNX2 a potential therapeutic target for blocking metastasis and further disease progression." (PMID 37759525, 2023).
tumor (continued). "Tumor suppressor miR-218 has inverse correlation with the ‘master switch’ runt-related transcription factor 2 (RUNX2), which controls several genes involved in the development of osteoblasts." (PMID 36778005, 2023). "RUNX2 is involved in the progression of various human tumours by regulating cell proliferation, angiogenesis, cancer stemness, and metastasis." (PMID 37759525, 2023). "Homozygous deletion of Runx2 induced dynamic alteration of tumor component and modification in the distribution of HEY1-NCOA2 DNA-binding peaks." (PMID 37212282, 2023). "RUNX2 is thought to relate to the proliferation, invasion, and metastasis of diverse malignant tumor cells." (PMID 36200301, 2023). "RUNX family transcription factor 1 (RUNX1), a tumor suppressor, and RUNX2 have contradictory regulatory effects on EMT in BRCA." (PMID 38235137, 2023). "Concurrent and emerging studies indicate the critical role of RUNX2 in orchestrating cancer progression in various tumor types." (PMID 37108164, 2023). "RUNX2-mediated malignancy was shown by the increased tumor growth in nude mice in a xenograft model." (PMID 37108164, 2023). "Western blot analysis of ccRCC tissues derived from clinical tumor specimens revealed that SCD1 protein expression was in positive correlation with RUNX2 protein expression." (PMID 36200301, 2023). "After 4 weeks, an in vivo imaging system (IVIS) was used to detect tumor growth and invasion, of which RUNX2 k/in group was significantly advanced compared with the control group." (PMID 36897488, 2023). "Although Runx2 knockout resulted in significant delay in tumor onset, it also induced aggressive growth of immature small round cells." (PMID 37212282, 2023). "Many reports showed that increased RUNX2 expression enhances tumour cell migration and invasive properties." (PMID 37759525, 2023). "Six samples of GC tumour of the bone (samples 19–23, and 25 a and b) reveal between 30% and 70% RUNX2-positive GCs." (PMID 37509363, 2023). "The knockdown of Fam50a decreased the luciferase activity of these cells in Runx2-expressed tumor cells." (PMID 37150786, 2023). "With enough reduction of MM tumor cells, PIs are thought to enhance the levels of critical osteoblastogenesis-related TFs such as Runx2 and ATF4, and thereby rebuild bone in MM." (PMID 37039914, 2023). "In mice subcutaneously injected with MKN-45 cells (Control, si-NC and si-RUNX2), both tumor size and volumes were decreased following RUNX2 silencing." (PMID 37256183, 2023). "Previous findings confirmed higher RUNX2 expression in HCC patients than expression detected in non-tumour tissues or healthy controls." (PMID 37759525, 2023). "RUNX1 expression rose in the UVM as tumor grade increased, while RUNX2 expression increased in the STAD, ESCA, and KICH." (PMID 35522574, 2022). "The results revealed that the expression levels of RUNX1, RUNX2, RUNX3 were higher in tumor tissues than in normal tissues, especially the expression of RUNX2 and RUNX3." (PMID 36092942, 2022). "According to the qChIP assays, knockdown of either RUNX2 or MTA1 consistently led to a dramatic increase in histone pan-H3 acetylation at the promoters of target tumor suppressor genes." (PMID 35534547, 2022). "Various studies have extensively documented the involvement of RUNX2 in tumor development, progression, and metastasis." (PMID 36231060, 2022). "Experimental methods of tumor cell migration and invasion showed that the number of oral squamous cells in the Runx2 si-RNA group crossed the stromal gel significantly less than that in the stable expression control group." (PMID 35342401, 2022). "The selected protumorigenic genes (Lrp5, MMP9, Runx2, TGFβ, and Snail) were downregulated in Oct4 CM-treated 4T1.2 parental cells, while they were elevated in Oct4-overexpressing tumor cells and reduced in Oct4-silenced tumor cells." (PMID 35547745, 2022). "In these cancers, TRβ1 has been considered to function as a tumor suppressor, and Runx2 as an oncogene." (PMID 36497320, 2022).
tumor (continued). "Casticin promotes AML cell apoptosis but inhibits AML cell proliferation in vitro and tumor growth in vivo by upregulating miR-338-3p, which targets RUNX2 and thereafter inactivates PI3K-Akt signaling pathway." (PMID 35765408, 2022). "Among the candidates, we noticed that RUNX2, which was involved in tumor growth, invasion, and metastasis, had been reported to be increased by hypoxia." (PMID 35110544, 2022). "Previously, hsa-miR-338-3p was reported to be an OS tumor suppressor that targeted RUNX2 and CDK4 through the MAPK pathway." (PMID 35151325, 2022). "In NSCLC, the microRNA-130a-5p/RUNX2/STK32A network modulates tumor proliferation, metastasis, and invasion." (PMID 36551878, 2022). "Consistently, TNFα upregulated Runx2, a tumor-promoting transcription factor, and Snail, a regulator of EMT, in SW1353 CS cells." (PMID 35804814, 2022). "RUNX2 induces the expression of various genes involved in tumor progression, including VEGF, MMP9, OPN, SNAI 1 and 2, TWIST1 and TIMP13, and activates signaling pathways such as mTORC2, PTEN/PI3K/AKT and NF-κB." (PMID 35805994, 2022). "In fact, RUNX2 is abnormally expressed in metastatic PCa cells where it facilitates tumor growth and osteolysis possibly through a RUNX2/Smad signaling axis." (PMID 35406450, 2022). "The results showed the upregulation of RANK-L, RANK, OPN, CXCR4, RUNX2 and FLT1 and the downregulation of OPG and CXCL12 genes, underlining their involvement and promising role in these neoplasms." (PMID 35203581, 2022). "Other oncogenes, such as CDC5L (cell division cycle 5-like involved in G2 cell cycle progression and tumor growth) or RUNX2 (Runt-related transcription factor 2 in osteoblastic differentiation and known oncogene in OS), are also recurrently amplified in OS." (PMID 35884563, 2022). "After 45 days, the lungs in the RUNX2‐knockdown group had a lower number of metastatic tumours compared to the empty vector group." (PMID 36264762, 2022). "RUNX2, a key molecule in the transformation of bone marrow mesenchymal stem cells to osteoblasts, which is also involved in tumor invasion and metastasis, was significantly upregulated in all analyzed cases." (PMID 35203581, 2022). "The expression of Runx2 in tumor tissues was decreased after miR-23a-3p-transfected CAL-27 cells were tumorigenic." (PMID 35342401, 2022). "RUNX2, as a lineage-specific transcription factor, participates in tumor metastasis and osteogenesis." (PMID 33413642, 2021). "RUNX2 is a member of the Runt-related transcription factor (Runx) family, and is involved in various biologic processes, including tumor suppression." (PMID 34093832, 2021). "Before examining potential tumor suppressors, we found that the levels of IL1β, Runx2, MMP9, TGFβ, and Snail in EO771 cells were downregulated by osteocyte-derived CM, and their levels were further reduced by the overexpression of the three selected genes." (PMID 33802279, 2021). "Inhibition of AKT in this tumor entity reduces the levels of pro-metastatic PTHrP and Osteonectin as well as Osteocalcin, which are RUNX2-dependent proteins." (PMID 34064589, 2021). "For example, runt-related transcription factor 2 (RUNX2) contributes to tumor progression by upregulating the expression of receptor tyrosine kinases and thereby mediating BRAFi resistance." (PMID 34071193, 2021). "The cancer cell survival suppressive effect of dipyridamole was paralleled by a reduction of the HMGB1/RAGE axis, and proliferation- and migration-related β-catenin, YAP1, Runx2, TGFβ1/Smad, and cyclin D1 in in vitro and in vivo tumor growth models." (PMID 33669632, 2021). "The Lrp5-dependent mechanism was evident since Lrp5-overexpressing osteocytes inhibited the growth of tumor spheroids and Lrp5-silenced osteocytes upregulated tumorigenic genes such as Runx2, MMP9, Snail, and TGFβ." (PMID 33450808, 2021).